CDS2 (CDP-diacylglycerol synthase 2)
Description:
Catalyzes the conversion of phosphatidic acid (PA) to CDP-diacylglycerol (CDP-DAG), an essential intermediate in the synthesis of phosphatidylglycerol, cardiolipin and phosphatidylinositol. Exhibits specificity for the nature of the acyl chains at the sn-1 and sn-2 positions in the substrate, PA and the preferred acyl chain composition is 1-stearoyl-2-arachidonoyl-sn-phosphatidic acid. Plays an important role in regulating the growth and maturation of lipid droplets which are storage organelles at the center of lipid and energy homeostasis.
Tractability: Antibody: UniProt predicts a signal peptide or a membrane-spanning region. PROTAC: ubiquitination databases record sites on it; its protein half-life has been measured.
Target class: Enzyme; Transferase
Gene: Protein-coding gene on chromosome 20 (5,126,879 to 5,197,887, forward strand). Ensembl gene ENSG00000101290.
Subcellular location: Endoplasmic reticulum membrane
Subcellular location (Human Protein Atlas): Endoplasmic reticulum
Pathways (Reactome):
Metabolism: Synthesis of PG
Gene Ontology:
Molecular function: phosphatidate cytidylyltransferase activity; protein binding; transferase activity, transferring phosphorus-containing groups
Biological process: CDP-diacylglycerol biosynthetic process; lipid droplet formation; phosphatidylglycerol biosynthetic process
Cellular component: endoplasmic reticulum; endoplasmic reticulum membrane; membrane; mitochondrial inner membrane
Genetic constraint (gnomAD): Loss-of-function variants: 28 observed, 40.65 expected, observed/expected ratio (o/e) 0.69, 90% interval 0.51 to 0.94. The upper end of that interval is the gene's LOEUF score, 0.94, which puts it in group 4 of 6, group 1 being the genes least tolerant of losing a copy. Missense variants: 318 observed, 506.8 expected, observed/expected ratio (o/e) 0.63, 90% interval 0.57 to 0.69. Synonymous variants: 184 observed, 194.3 expected, observed/expected ratio (o/e) 0.95, 90% interval 0.84 to 1.07.
Homologues: Orthologues: chimpanzee CDS2 (99% identical), macaque CDS2 (99% identical), dog CDS2 (96% identical), mouse Cds2 (96% identical), rabbit CDS2 (96% identical), rat Cds2 (95% identical), pig CDS2 (94% identical), guinea pig CDS2 (93% identical), tropical clawed frog cds2 (85% identical), zebrafish cds2 (83% identical), Drosophila melanogaster Cds (58% identical), Caenorhabditis elegans cdgs-1 (51% identical). Paralogues in human: CDS1 (72% identical).
Diseases named in the same sentence as CDS2 in open-access papers:
CDS2 is named in the same sentence as 10 diseases in open-access papers, as found by Europe PMC text mining. Sharing a sentence is not in itself a finding about the gene and the disease. The quoted sentences say what the papers report.
uveal melanoma (2 papers, 2024 to 2025). A melanoma derived from melanocytes of the uveal tract. "CDS2 has attracted increasing attention recently as a potential target for anti-angiogenic treatment of tumours and for treatment of uveal melanomas driven by mutationally enhanced PLC signalling." (PMID 39312194, 2024). "Notably, CDS2 disruption in grafted cells resulted in significantly reduced uveal melanoma cell expansion, which prolonged the time to the tumor growth limit, when xenografted mice were fed a Dox-containing diet (625 mg kg−1; ENVIGO)." (PMID 40615675, 2025). "Among our 76 uveal melanoma-specific essential genes and 105 synthetic lethal gene pairs, we identified and validated the CDP-diacylglycerol synthase 2 gene (CDS2) as a genetic dependency in the context of low CDP-diacylglycerol synthase 1 gene (CDS1) expression." (PMID 40615675, 2025).
tumor (6 papers, 2019 to 2025). "In tumor models, CDS2 deficiency enhanced the level of tumor-secreted VEGFA, which in-turn trapped tumors into a VEGFA-induced vessel regression situation, leading to suppression of tumor growth." (PMID 31501519, 2019). "In tumor models, CDS2 deficiency suppresses tumor growth by regulating tumor-secreted VEGFA." (PMID 34722508, 2021). "LLC or B16-F10 allografted mice treated with either of the two Cds2 vMOs show decreased tumor volume and decreased final tumor weight compared to control vMO-injected mice." (PMID 32139674, 2020). "Daily co-injection of PIP2 liposomes into LLC-allografted mice treated with the Cds2 vMO does reverse tumor growth and vascular density defects noted with Cds2 vMO treatment alone." (PMID 32139674, 2020). "Tumor-associated ECs from LLC-allografted, Cds2 vMO-treated mice show markedly reduced levels of PIP2, p-AKT, and p-ERK1/2." (PMID 32139674, 2020). "To determine if Cds2 vMO treatments have direct effects on tumor cell proliferation, we exposed isolated B16-F10 or LLC cells in vitro to the estimated comparable doses of Cds2 vMO that they would encounter in vivo and measured proliferation rates." (PMID 32139674, 2020). "Quantitation of tumor vessel density in CD31 immunostained sections revealed an ~70–80% reduction in vessel area in LLC tumor allografts from either of the Cds2 vMO-treated animals compared to controls." (PMID 32139674, 2020). "LLC-allografted mice treated with either of the two Cds2 vMOs show decreased tumor volume and decreased final tumor weight compared to control vMO-injected mice." (PMID 32139674, 2020). "Quantitation of tumor vessel density in CD31 immunostained sections revealed ~60–80% reduction in vessel area in either LLC or B16-F10 tumor allografts from Cds2 vMO-treated animals compared to controls." (PMID 32139674, 2020). "Importantly, tumor and liver/lung ECs from the same animals show comparable reductions in CDS2 protein levels." (PMID 32139674, 2020). "Live imaging analysis uncovered the presence of reverse migration of the angiogenic endothelium in cds2 mutant zebrafish upon VEGFA stimulation, and endothelium regression also occurred in postnatal retina and implanted tumor models in mice." (PMID 31501519, 2019). "In vitro exposure of LLC or B16-F10 tumor cells to Cds2 vMO does not alter proliferation rates, suggesting the reduced tumor growth rates we note in our in vivo vMO studies are not the result of inhibitory effects on the tumor cells themselves." (PMID 32139674, 2020). "Because TC-1 tumor cells themselves expressed high level of COL4, ultrasound imaging assay showed gradually reduced blood flow inside TC-1 tumors after endothelium-specific Cds2 KO in the recipient mice." (PMID 31501519, 2019). "In contrast to the tumor EC findings, EC from lungs and livers collected from the same LLC-allografted Cds2 vMO-treated mice that the tumors were isolated from show no reduction in levels of PIP2, p-AKT, or p-ERK1/2." (PMID 32139674, 2020).
cancer (2 papers, 2025 to 2026). A tumor composed of atypical neoplastic, often pleomorphic cells that invade other tissues. "Our data imply that CDS2 inhibition may be explored to eliminate particularly mesenchymal-like cancers, which are common, highly metastatic and relatively resistant to therapy." (PMID 40615674, 2025). "Thus, CDS2 may serve as a pharmacologically tractable target in mesenchymal-like cancers." (PMID 40615674, 2025).
cardiovascular diseases (1 paper, 2020). "Analyzed genes were associated with cardiovascular diseases and risk factors (TBC1D22A, WNK1), bone mineral density (HDAC5), body weight (PABPC3), glycerophospholipid metabolism (CDS2), Notch signaling (HDAC5), RNA transport and degradation (PABPC3)." (PMID 32344947, 2020).
infection (1 paper, 2023). The state of being infected such as from the introduction of a foreign agent such as serum, vaccine, antigenic substance or organism. "Accordingly, DRE sites in lipid-related genes such as Lipoprotein lipase (Lpl) and CDP Diacylglycerol Synthase 2 (Cds2) were upregulated after infection." (PMID 37081881, 2023).
CDS2 also shares sentences with these, for which no sentence is quoted: breast carcinoma (1 paper); congestive heart failure (1); Obesity (1); psychiatric disorder (1); steatosis (1).